RNU6-486P (RNA, U6 small nuclear 486, pseudogene)
Gene: Small nuclear RNA gene on chromosome 3 (180,581,057 to 180,581,163, forward strand). Ensembl gene ENSG00000199986.
Homologues: Orthologues: chimpanzee U6 (99% identical), macaque U6 (91% identical), guinea pig U6 (85% identical), mouse Gm25021 (85% identical), mouse Gm29163 (85% identical), pig U6 (85% identical), rabbit U6 (85% identical), rat LOC120094984 (75% identical). Paralogues in human: RNU6-338P (88% identical), RNU6-1124P (87% identical), RNU6-842P (87% identical), RNU6-24P (86% identical), RNU6-529P (86% identical), RNU6-726P (86% identical), RNU6-1011P (85% identical), RNU6-1083P (85% identical), RNU6-1117P (85% identical), RNU6-12P (85% identical), RNU6-1310P (85% identical), RNU6-13P (85% identical), and 1285 more.